EDN1 (endothelin 1)
Diseases named in the same sentence as EDN1 in open-access papers (continued):
Sharing a sentence is not in itself a finding about the gene and the disease.
rheumatoid arthritis (12 papers, 2005 to 2024). A chronic, systemic autoimmune disorder characterized by inflammation in the synovial membranes and articular surfaces. "Endothelin 1 is a potent vasoconstrictor that has been linked to graft rejection and to inflammatory events including pain, fever, cell migration and rheumatoid arthritis." (PMID 19295914, 2009). "High levels of plasma EDN1 have been observed in rheumatoid arthritis." (PMID 34746233, 2021). "Furthermore, in rheumatoid arthritis patients who carry the T-T haplotype in EDN1 SNPs (rs1800541 and rs5370), increased systolic blood pressure and high EDN1 plasma levels emerged." (PMID 24063765, 2013).
Arrhythmia (11 papers, 2007 to 2026). Any cardiac rhythm other than the normal sinus rhythm. "The elevated levels of endothelin 1 or angiotensin II (both of which are synthesized within the myocardium, among others) also could explain why isolated NEP inhibition by Sac alone did not have any effects on functional parameters or arrhythmia in our in vitro study." (PMID 35865376, 2022).
lung diseases (11 papers, 2006 to 2025). "Endothelin-1 (ET-1) is a potent peptide hormone known for its vasoconstrictive and proliferative effects and plays a critical role in the pathogenesis of various pulmonary diseases." (PMID 40476215, 2025).
breast tumor (10 papers, 1995 to 2026). ",202, 203, 204, 205,212 GPER is involved in the responses upon endothelin-1 (ET-1) exposure, such as the migratory behavior of breast tumor cells and the formation of tube-like structures in human umbilical vein endothelial cells." (PMID 41141392, 2026). "Recently, angiotensin II type 1 receptor (ATR1) and endothelin 1 (ET1) have been shown to play a role in breast tumor growth." (PMID 35743613, 2022). "This will unravel in detail the inter-relationship between EDN3 expression loss and upregulation of EDN1/2 and EDNRA/B as well as its association with breast tumour progression." (PMID 19527488, 2009). "However, TNC and endothelin-1 (ET-1, also known as EDN1) were identified as inducers of lymphatic vessels upon podoplanin overexpression in MCF7 breast tumor xenografts." (PMID 36102918, 2022). "Endothelin-1 (ET-1) levels are elevated in human breast tumours compared with normal and benign tissues, and in the presence of insulin-like growth factor 1 (IGF-I) ET-1 is a potent mitogen for human breast fibroblasts." (PMID 7880721, 1995).
hepatocellular carcinoma (10 papers, 2013 to 2024). A malignant tumor that arises from hepatocytes. "In a rat hepatoma model, it has been demonstrated that exogenous addition of EDN1 enhances hepatoma cell growth in a dose‐dependent manner, whereas an endothelin receptor antagonist inhibits tumor growth." (PMID 34766114, 2020). "The increased expression of EDN1 has been observed in many malignant tumors, including breast, colorectal, prostate, pancreatic, and hepatocellular carcinomas." (PMID 24416389, 2014). "We previously have shown that EDN1 expression at the RNA and protein levels was increased in hepatocellular carcinoma samples when compared to normal tissues." (PMID 24416389, 2014). "Hepatoma cell growth increases upon the exogenous addition of EDN1 in a dose-dependent manner." (PMID 24416389, 2014). "miR-1 inhibits EDN1 expression and leads to attenuation of hepatoma cell proliferation." (PMID 24416389, 2014). "Interestingly, the miR-1 target endothelin-1 (ET-1) is a growth promoting peptide that plays an oncogenic role in hepatocellular carcinoma by significantly increasing its ability to proliferate." (PMID 24029073, 2013). "The tissue concentrations of EDN1, big ET-1, and the ETA receptor were significantly increased in hepatoma tissue compared to normal liver tissue." (PMID 24416389, 2014).
Pruritus (10 papers, 2012 to 2024). Pruritus is an itch or a sensation that makes a person want to scratch. "Endothelin-1 (ET-1) is well known as the most potent vasoconstrictor, and can evoke histamine-independent pruritus." (PMID 32528072, 2020).
Right ventricular hypertrophy (10 papers, 2011 to 2026). In this case the right ventricle is more muscular than normal, causing a characteristic boot-shaped (coeur-en-sabot) appearance as seen on anterior- posterior chest x-rays. "Rats with right ventricular hypertrophy had a decreased expression of the endothelin-B receptor (EDNRB) in the lung, together with an increased protein content of endothelin-1 and an increased expression of ACTA2A." (PMID 39452062, 2024).
coronary atherosclerosis (9 papers, 2017 to 2025). Atherosclerosis of the coronary vasculature. "A seminal study demonstrated a possible mechanism involving inhibition of endothelin-1 (ET-1) synthesis, a vasoactive peptide that is associated with the development of coronary atherosclerosis." (PMID 35336690, 2022).
glioblastoma (9 papers, 2003 to 2026). The most malignant astrocytic tumor (WHO grade IV). "In glioblastomas, YAP confers invasiveness by upregulating miR296-3p as well as other canonical YAP targets (neuronal growth regulator 1 (NEGR1), matrix metalloproteinase 1 (MMP1), endothelin 1 (EDN1), CYR61, and CTGF)." (PMID 34439395, 2021).
glioma (9 papers, 2012 to 2026). A benign or malignant brain and spinal cord tumor that arises from glial cells (astrocytes, oligodendrocytes, ependymal cells). "Hypoxia promotes high expression levels of circRNA 101491 (circ-101491) in the extracellular region of glioma cells, whereas activation of the circRNA 101491/miRNA 125b-5p/endothelin 1 (circ-101491/miR-125b-5p/EDN1) axis is associated with the malignant progression of glioma." (PMID 37753074, 2023). "In glioma high levels of hypoxic exosomal circ101491 correlate with disease aggressiveness and poor prognosis by promoting progression Via the circ101491/miR-125b-5p/EDN1 axis." (PMID 41301888, 2025). "They proposed that the circ101491/miR-125b-5p/EDN1 regulatory axis might play a role in the malignant progression of glioma." (PMID 37993261, 2023). "RGMB, EDN1, SEMA3C and NRTN have been indicated to regulate olfactory neurogenesis, mesenchymal stem cells regeneration, tumorigenicity of glioma stem cells and neurite outgrowth, respectively." (PMID 35511361, 2022).
hypertrophic cardiomyopathy (9 papers, 2019 to 2025). A condition in which the myocardium is hypertrophied without an obvious cause. "DOX increases the level of endothelin-1 (ET-1) in cardiomyocytes and leads to hypertrophic cardiomyopathy via the epidermal growth factor (EGF) receptor signaling pathway." (PMID 41155422, 2025). "Endothelin-1, its membrane receptor and IGF1 gene expressions were significantly upregulated by T2D, leading to a predicting activation of concentric hypertrophic cardiomyopathy pathways (point A)." (PMID 38978010, 2024).
hyperuricemia (9 papers, 2013 to 2021). An abnormally high level of uric acid. "Here we demonstrated that hyperuricemia conditions induced renal damage with tubular injury and kidney fibrosis through activation of Endothelin-1 (ET-1) and fibroblast expansion." (PMID 29089036, 2017). "Elevated serum levels of endothelin-1 (ET-1) have been found in rats with hyperuricemia." (PMID 30993112, 2019).
periodontitis (9 papers, 2016 to 2024). An acute or chronic inflammatory process that affects the tissues that surround and support the teeth. "Endothelin-1 (ET-1) and interleukin-1β (IL-1β) is increased in periodontitis and is linked to inflammatory cytokines amongother variables." (PMID 39917223, 2024). "Additional research on periodontitis has documented alterations in various inflammatory biomarkers, including an upregulation of endothelin-1, transforming growth factor-beta 1, and vascular endothelial growth factor." (PMID 39074834, 2024). "Saliva and sulcular levels of inflammatory biomarkers associated with chronic periodontitis could be investigated, such as free radicals, cytokines, matrix metalloproteinase (MMP)-2 and -8, tissue inhibitor of metalloproteinases (TIMP)-2 complex, or endothelin-1, for instance." (PMID 32218125, 2020).
type 1 diabetes (9 papers, 2015 to 2022). "Six pathways including neuroinflammation signaling pathway, type I diabetes mellitus signaling, ERK5 signaling, NF-κB signaling, synaptic long term potentiation, and endothelin-1 signaling were enriched in E-MTAB-7961 splenic Treg." (PMID 34084175, 2021).
arteriosclerosis (8 papers, 2012 to 2023). A vascular disorder characterized by thickening and hardening of the walls of the arteries. "A damage of vascular endothelial cell is known to be a decisive factor of conditional pathophysiology of cardiovascular disease as arteriosclerosis which is caused by secretion of cell adhesion molecules, endothelin-1 (ET-1) and inflammatory cytokine." (PMID 26961224, 2016). "Similarly, endothelin-1 (ET-1), which is linked to vascular inflammation, may also play an essential role in the development of arteriosclerosis along with adhesion molecules." (PMID 34257675, 2021).
coronary vasospasm (8 papers, 2011 to 2025). Sudden coronary artery smooth muscle contraction leading to lumen constriction and decreased blood flow. "5-FU and its active metabolites can impair the normal functioning endothelium, leading to an elevated release of endothelin-1, a vasoconstrictor, and a diminished release of prostacyclin, a vasodilator causing coronary vasospasm." (PMID 40994918, 2025). "Cocaine stimulates the release of endothelin-1 which causes vasoconstriction in endothelial cells and inhibits the production of vasodilating nitric oxide, resulting in coronary artery spasms that can explain the CF-decrease in our experiments." (PMID 32377925, 2020). "In addition, Sirt1-mediated NF-κB deacetylation hinders the myosin light-chain kinase/myosin light chain-2 (MLCK/MLC2) pathway and endothelin-1 (ET-1) expression, thus alleviating coronary artery spasm." (PMID 35387565, 2022). "The occurrence of coronary vasospasm in patients with infectious myocarditis may relate to vasoactive substances, like the powerful vasoconstrictors Endothelin-1 (ET-1) and TXA2." (PMID 29536322, 2018).
endometriosis (8 papers, 2018 to 2023). The growth of functional endometrial tissue in anatomic sites outside the uterine body. "Study has found that bradykinin (BK) is involved in the occurrence of EM pain, and the activation of BKR induces endothelin-1 in endometriosis lesions, and that can cause pain." (PMID 36708425, 2023). "Molecular pathways dysregulated in CVD are also affected in endometriosis; vascular dysfunction is associated with upregulation of endothelin-1 (ET-1) production that intervenes in endometriosis-altered pain response." (PMID 36359302, 2022). "Secondly, the aberrant expression of miR-375 in ectopic stromal cells may contribute to higher levels of EDN1 in lesions, which can be associated with pain mechanisms or be involved in the regulation of invasive growth and cell proliferation in endometriosis development." (PMID 30487429, 2018). "These microRNAs may regulate the expression of the transcription factors HOXA9 and HOXA10 and the endothelin 1 gene (EDN1) playing a role in vascular homeostasis, which may be related to the development of endometriosis." (PMID 34638893, 2021). "miR-375 by targeting EDN1 could be involved in the regulation of invasive growth and cell proliferation in endometriosis development." (PMID 32850438, 2020). "Thus, the suppression of EDN1 transcription by the overexpression of miR-375 could potentially be used as a therapy for endometriosis-related pain or as a strategy to prevent the dissemination of endometrial mesenchymal stem cells outside the uterus." (PMID 30487429, 2018). "miR-202, for example, was found to promote endometriosis by inhibiting SOX6, and downregulation of miR-375 alleviated the suppression of endothelin 1 (EDN1) in ectopic stromal cells, which in turn contributed to the development of endometriosis." (PMID 32112646, 2020).
interstitial lung disease (8 papers, 2008 to 2025). A diverse group of lung diseases that affect the lung parenchyma. "Accordingly, different groups have found an association between IP10 or endothelin 1 (ET-1) and different interstitial lung diseases (ILDs)." (PMID 23056449, 2012).
left ventricular hypertrophy (8 papers, 2007 to 2026). Enlargement of the LEFT VENTRICLE of the heart. "Carriers of the EDN1 T-1370G G allele presented with significantly increased left ventricular hypertrophy." (PMID 26121692, 2015). "This makes it unlikely that excessive left ventricular hypertrophy triggers the observed changes in endothelin-1 and ACTA2 in the lungs." (PMID 39452062, 2024).
multiple sclerosis (8 papers, 2008 to 2025). A progressive autoimmune disorder affecting the central nervous system resulting in demyelination. "Increases in circulating endothelin-1 are also associated with other diseases like multiple sclerosis, fibromyalgia, and transiently during optic neuritis." (PMID 27090783, 2016).
retinal ischemia (8 papers, 2011 to 2024). A ischemic disease that involves the retina. "Endothelin-1 (ET-1) overactivity has been implicated as a factor contributing to glaucomatous neuropathy, and it has been utilized in animal models of retinal ischemia." (PMID 37566067, 2023). "Magnesium deficiency would contribute to increased vascular smooth Ca2+, endothelin-1, and thromboxane A2 and decreased prostacycline, which potentially result in vasoconstriction and retinal ischemia." (PMID 35989402, 2023).
viral infection (8 papers, 2020 to 2026). "Increased cytokines production during viral infection would increase the levels of endothelin-1 in the cells (Bouallegue, BouDaou & Srivastava, 2007)." (PMID 32566414, 2020).
Chagas disease (7 papers, 2008 to 2019). A parasitic infection caused by Trypanosoma cruzi. "Increased plasma levels of endothelin-1, which is a marker of endothelial activation, were also found in Chagas disease patients with severe cardiac dysfunction, compared with those in uninfected subjects." (PMID 31199841, 2019).
Constipation (7 papers, 2019 to 2025). Infrequent or difficult evacuation of feces. "In the present study, the expression levels of the EDN1 and NXPE4 genes were upregulated 2.06- and 2.00-fold, respectively, during C3 deficiency-induced constipation." (PMID 39273477, 2024).
diabetic cardiomyopathy (7 papers, 2015 to 2025). Diabetic cardiomyopathy is a disorder of the heart muscle in people with diabetes. "Impairments of endothelin-1 (ET-1) signaling and mTOR pathway have been implicated in diabetic cardiomyopathies." (PMID 36430296, 2022). "Diabetic cardiomyopathy is associated with changes in the expression and bioavailability of vasoactive factors released from the endothelium of coronary microvasculature, including upregulation of endothelin-1 (ET-1) and downregulation of nitric oxide (NO)." (PMID 25629059, 2015). "We screened for potential therapeutics that can regulate the activity of TFs upstream of EDN1 to affect the pathophysiology of diabetic cardiomyopathy." (PMID 36046789, 2022). "In human aortic ECs (HAECs) and HUVECs, high glucose also induces EndMT through positive regulators, such as angiotensin II, poly (ADP-ribose) polymerase 1 (PARP-1), endothelin 1 (ET-1), Smad, Akt, p38, and ERK, contributing to diabetic cardiomyopathy." (PMID 29515588, 2018).
dilated cardiomyopathy (7 papers, 2013 to 2024). Cardiomyopathy which is characterized by dilation and contractile dysfunction of the left and right ventricles. "It has also been shown that endothelin-1 overexpression causes the heart to develop dilated cardiomyopathy and increases in the expression of pro-inflammatory cytokines." (PMID 37240239, 2023). "In conclusion, our data show an increase in endothelin-1 transcript levels as disease progresses from healthy to dilated cardiomyopathy with ascites, while a corresponding decrease in TGF-β2 and TGF-β3 is observed and seems independent of temperature conditions." (PMID 24286074, 2013). "This study aimed to investigate the predictive value of Big endothelin-1(ET-1) for left ventricular reverse remodeling (LVRR) and prognosis in patients with dilated cardiomyopathy (DCM)." (PMID 36835899, 2023).
idiopathic pulmonary arterial hypertension (7 papers, 2014 to 2025). A sporadic form of pulmonary arterial hypertension (PAH) characterized by elevated pulmonary arterial resistance leading to right heart failure. "Similarly in another study, adiponectin, leptin, and endothelin-1 levels in idiopathic pulmonary arterial hypertension (IPAH) patients’ serum were found to be higher than those in healthy volunteers." (PMID 30791536, 2019). "Endothelin-1, a potent vasoconstrictor and mitogen for smooth muscle cells produced by endothelial cells, has been found to have elevated plasma levels in patients with both Idiopathic Pulmonary Arterial Hypertension (IPAH) and Chronic Thromboembolic Pulmonary Hypertension (CTEPH)." (PMID 39171327, 2024). "Still regarding mediators, there is evidence of elevated serum levels of endothelin-1 in patients with IPF, as well as in patients with idiopathic pulmonary arterial hypertension." (PMID 28659997, 2017). "A large number of these patients do not have PH; and whereas treatment with bosentan, an endothelin-1 antagonist, was effective to treat idiopathic pulmonary arterial hypertension, it did not produce improvement in patients with IPF and PH." (PMID 28659997, 2017).
liver cirrhosis (7 papers, 2008 to 2025). "Patients with liver cirrhosis have elevated plasma endothelin-1, which binds to its pulmonary endothelin-1B receptor and triggers the inducible and endothelial nitric oxide (iNOS and eNOS) synthases." (PMID 30795758, 2019).
respiratory failure (7 papers, 2011 to 2025). The significant impairment of gas exchange within the lungs resulting in hypoxia, hypercarbia, or both, to the extent that organ tissue perfusion is severely compromised. "Mice lacking the Edn1 gene die of respiratory failure at birth and show severe craniofacial abnormalities, as well as cardiovascular defects." (PMID 21699702, 2011).
sarcopenia (7 papers, 2012 to 2025). Progressive decline in muscle mass due to aging which results in decreased functional capacity of muscles. "In vivo studies have shown that endothelin‐1 (ET‐1) promotes fibrosis and senescence in cultured myoblasts in aging sarcopenia." (PMID 40034063, 2025).
sickle cell disease (7 papers, 2016 to 2024). Sickle cell anemias are chronic hemolytic diseases that may induce three types of acute accidents: severe anemia, severe bacterial infections, and ischemic vasoocclusive accidents (VOA) caused by sickle-shaped red blood cells obstructing small blood vessels and capillaries. "Several of these miRNAs were found to interact in the molecular pathways regulating the inflammation action of Endothelin-1, cardiovascular disease, and sickle cell disease." (PMID 26854194, 2016).
transient cerebral ischemia (7 papers, 2016 to 2022). "This approach was evaluated in rat brain using malonate-perfusion (10–50 mM) and endothelin-1 (ET-1)-induced transient cerebral ischemia." (PMID 31569792, 2019). "Using endothelin-1 (ET-1) to cause transient cerebral ischemia does not require complicated surgical procedures and has been well established in rodents and lower primates." (PMID 27347877, 2016).
vasculitis (7 papers, 2008 to 2024). "One of the most relevant vasculitis-promoting factors triggered by T. cruzi infection is endothelin-1 (ET-1)." (PMID 30020318, 2018). "Among other vasculitis-promoting factors, T. cruzi infection triggers myocardial overexpression and increased plasma levels of endothelin-1 (ET-1) in mice and chronic chagasic patients, which correlate with heart dysfunction." (PMID 23409199, 2013). "Henoch Schonlein purpura (HSP) is a common vasculitis of small vessels whereas endothelin-1 (ET-1) is usually reported elevated in vasculities and systematic inflammation." (PMID 18764935, 2008).